ENSG00000284952 (novel transcript)
Gene: Protein-coding gene on chromosome 3 (155,763,043 to 155,854,442, reverse strand). Ensembl gene ENSG00000284952.
Genetic constraint (gnomAD): Missense variants: 242 observed, 336.41 expected, observed/expected ratio (o/e) 0.72, 90% interval 0.65 to 0.8. Synonymous variants: 141 observed, 135.48 expected, observed/expected ratio (o/e) 1.04, 90% interval 0.91 to 1.2.